CLEC4D (C-type lectin domain family 4 member D)
Description:
Calcium-dependent lectin that acts as a pattern recognition receptor (PRR) of the innate immune system: recognizes damage-associated molecular patterns (DAMPs) of pathogen-associated molecular patterns (PAMPs) of bacteria and fungi. The PAMPs include alpha-mannans on C.albicans hypheas and mycobacterial trehalose 6,6'-dimycolate (TDM). Interacts with signaling adapter Fc receptor gamma chain/FCER1G, likely via CLEC4E, to form a functional complex in myeloid cells (By similarity). Binding of mycobacterial TDM or C.albicans alpha-mannans to this receptor complex leads to phosphorylation of the immunoreceptor tyrosine-based activation motif (ITAM) of FCER1G, triggering activation of SYK, CARD9 and NF-kappa-B, consequently driving maturation of antigen-presenting cells and shaping antigen-specific priming of T-cells toward effector T-helper 1 and T-helper 17 cell subtypes. The heterodimer formed with CLEC6A is active against fungal infection. Functions as an endocytic receptor. May be involved in antigen uptake at the site of infection, either for clearance of the antigen, or for processing and further presentation to T-cells.
Synonyms: CLEC-6; Dectin-3; CD368; CLECSF8; MCL; Mpcl; CLEC6
Tractability: Antibody: UniProt places it where antibodies can reach, with high confidence; its Gene Ontology location is reachable by antibodies, with high confidence; UniProt predicts a signal peptide or a membrane-spanning region. PROTAC: ubiquitination databases record sites on it.
Gene: Protein-coding gene on chromosome 12 (8,509,475 to 8,522,366, forward strand). Ensembl gene ENSG00000166527.
Subcellular location: Cell membrane
Pathways (Reactome):
Immune System: Dectin-2 family; Neutrophil degranulation
Gene Ontology:
Molecular function: D-mannose binding; pattern recognition receptor activity; protein binding; carbohydrate binding; immunoglobulin receptor binding
Biological process: antifungal innate immune response; positive regulation of myeloid dendritic cell activation; positive regulation of canonical NF-kappaB signal transduction
Cellular component: plasma membrane; external side of plasma membrane; ficolin-1-rich granule membrane; specific granule membrane; tertiary granule membrane
Genetic constraint (gnomAD): Loss-of-function variants: 12 observed, 11.9 expected, observed/expected ratio (o/e) 1.01, 90% interval 0.64 to 1.61. The upper end of that interval is the gene's LOEUF score, 1.61, which puts it in group 6 of 6, group 1 being the genes least tolerant of losing a copy. Missense variants: 177 observed, 179.4 expected, observed/expected ratio (o/e) 0.99, 90% interval 0.87 to 1.12. Synonymous variants: 52 observed, 57.54 expected, observed/expected ratio (o/e) 0.9, 90% interval 0.72 to 1.14.
Homologues: Orthologues: chimpanzee CLEC4D (98% identical), macaque CLEC4D (89% identical), dog CLEC4D (67% identical), rabbit CLEC4D (66% identical), mouse Clec4d (62% identical), rat Clec4d (60% identical), zebrafish asgr1a (26% identical), Drosophila melanogaster tfc (23% identical), zebrafish asgr1c.2 (23% identical), Caenorhabditis elegans clec-266 (20% identical), zebrafish asgr1b (20% identical), zebrafish si:ch211-283g2.5 (18% identical), and 11 more. Paralogues in human: CLEC4C (41% identical), CLEC6A (40% identical), CLEC4E (35% identical), CLEC4A (33% identical), CLEC4M (29% identical), CD209 (28% identical), ASGR2 (26% identical), CD207 (26% identical), CLEC4G (26% identical), CLEC17A (25% identical), ASGR1 (24% identical), CLEC10A (23% identical), and 2 more.
Diseases named in the same sentence as CLEC4D in open-access papers:
CLEC4D is named in the same sentence as 145 diseases in open-access papers, as found by Europe PMC text mining. Sharing a sentence is not in itself a finding about the gene and the disease. The quoted sentences say what the papers report.
colitis (17 papers, 2016 to 2025). Inflammation of the colon. "It has been demonstrated that the deficiency of CLEC4D in the gut promotes the development of colitis by impairing antifungal immune responses." (PMID 36979470, 2023). "A recent study using Dectin-3-deficient (Clec4d-/-) mice showed their susceptibility to DSS-induced colitis." (PMID 35215155, 2022). "Since the C-Type Lectin domain containing 4D (CLEC4D) is the encoding gene for Dectin-3, Clec4d−/− mice were more susceptible to induced colitis due to the activation of the NF-κB signaling pathway." (PMID 33964975, 2021). "We found that Dectin-3-deficient (Clec4d-/-) mice were more susceptible to DSS-induced colitis compared with wild-type mice." (PMID 27280399, 2016). "Third, Clec4d-/- mice is more susceptible to DSS-induced colitis than wild-type mice, and C. tropicalis aggravates the development of colitis." (PMID 27280399, 2016). "Here we found that mice deficient in Dectin-3 (Clec4d-/-), a C-type lectin receptor that senses fungal infection, were more susceptible to dextran sodium sulfate (DSS)-induced colitis compared with wild-type mice." (PMID 27280399, 2016). "Given that C. tropicalis is an opportunistic pathogen, we further analyzed its role in the development of colitis in Clec4d-/- mice." (PMID 27280399, 2016). "First, C. tropicalis is an opportunistic pathogen, and its burden is specifically increased in Clec4d-/- mice during induction of colitis." (PMID 27280399, 2016). "Fluconazole treatment could significantly inhibit the proliferation of fungus in Clec4d-/- colitis mice." (PMID 27280399, 2016). "We found that only C. tropicalis increased in Clec4d-/- mice during colitis." (PMID 27280399, 2016). "Finally, anti-fungal therapy was effective in treating colitis in Clec4d-/- mice." (PMID 27280399, 2016). "On histological examination, intestinal epithelial cell appeared normal and no observed spontaneous colitis was found in Clec4d-/- mice." (PMID 27280399, 2016). "The specific fungal burden of Candida (C.)tropicalis was markedly increased in the gut after DSS treatment in Clec4d-/- mice, and supplementation with C. tropicalis aggravated colitis only in Clec4d-/- mice, but not in wild-type controls." (PMID 27280399, 2016). "To exclude the effect of fungal supplementation alone on colitis, we supplemented mice with C. tropicalis alone without DSS, and found that C. tropicalis could not induce colitis in both wild-type and Clec4d-/- mice without DSS treatment." (PMID 27280399, 2016).
COVID-19 (17 papers, 2020 to 2025). A disease caused by infection with severe acute respiratory syndrome coronavirus 2. "However, CLEC4D, as one of the CLEC4s, demonstrated a potential value in virus infection, including COVID-19." (PMID 36140771, 2022). "Samples with higher scores tended to have a higher probability of COVID-19, and significantly higher expressions of CLEC4D, DUSP13, and UNC5A were found in COVID-19 patients compared with those in healthy controls in GSE152641 and GSE171110." (PMID 36140771, 2022). "Genes involved in macrophage and neutrophils were over-expressed in patients infected with viruses (COVID-19 and INFL) compared to HLTY (“ascending” pattern, e.g. CLEC4D and CD55)." (PMID 34135895, 2021). "In conclusion, we constructed a three-gene signature to identify COVID-19, and CLEC4D, DUSP13, and UNC5A may be potential biomarkers for COVID-19 patients." (PMID 36140771, 2022). "Finally, a three-gene signature comprising CLEC4D, DUSP13, and UNC5A that can accurately distinguish COVID-19 patients and healthy controls in three datasets was constructed." (PMID 36140771, 2022).
tuberculosis (14 papers, 2015 to 2025). A chronic, recurrent infection caused by the bacterium Mycobacterium tuberculosis. "Both Clec4d and Clec5a are of high relevance as they contribute to the recognition of tuberculosis and dengue virus respectively." (PMID 29213115, 2017). "The CLEC4D gene is critical in infectious diseases, such as pulmonary tuberculosis (TB), as mycobacterial recognition is one of its vital functions." (PMID 39459398, 2024).
viral infection (10 papers, 2017 to 2025). "Furthermore, as previously demonstrated, Fcgr1 makes a contribution to arthritis pathology; Clec4a2 and Clec4d play essential roles in maintaining the homeostasis of immune system; Arg1 activity is important for wound healing functions and immune response to viral infections." (PMID 29197380, 2017).
fungal infections (9 papers, 2016 to 2022). "Dectin-3, a CLR also known as MCL/CLECSF8/Clec4d, functions as a pattern recognition receptor for sensing fungal infections by recognizing α-mannans." (PMID 27280399, 2016).
Sepsis (7 papers, 2020 to 2025). Sepsis is defined as life-threatening organ dysfunction caused by a dysregulated host response to infection. "Unexpectedly, the prognosis of sepsis was significantly associated with four of the five hub genes: HK3, GPR84, CLEC4D, and S100A12." (PMID 40821971, 2025). "Of note, a previous study demonstrated differential expression of CLEC4D between pediatric patients with sepsis and controls, similar to the present findings." (PMID 40821971, 2025). "And many of these genes (such as CD177, S100A12, and CLEC4D) played a critical role in sepsis pathology." (PMID 35739592, 2022). "Similarly, the genes screened by WGCNA such as CD177, S100A12, and CLEC4D have also been described to be important in the pathogenesis of sepsis." (PMID 35739592, 2022). "CXCR1 is one of the major chemokine receptors on polymorphionuclear neutrophils, and the involvement of polymorphionuclear neutrophils in sepsis is well recognized.CLEC4D, a member of Dectin-2 family, functions in resolution of inflammation, possibly through facilitating neutrophil turnover." (PMID 32151258, 2020). "This study identified four hub genes (CLEC4D, GPR84, S100A12, and HK3) with significant prognostic value in sepsis and predicted a ceRNA network (NEAT1-hsa-miR-495-3p-ELF1) regulating their expression." (PMID 40821971, 2025). "In contrast, a significant increase in the transcription of CLEC4D (C-type lectin domain family 4 member D), GCA (grancalcin), and ELANE (elastase, neutrophil expressed) was reported in the sepsis group as compared to the control." (PMID 34594344, 2021). "Among these genes, CLEC4D exhibited the highest prognostic value (AUC = 0.898) in distinguishing between sepsis survivors and non-survivors." (PMID 40821971, 2025).
cryptococcal infection (5 papers, 2017 to 2022). "Dectin-3 (also known as Clec4D, Clecsf8, MCL), which contains a short cytoplasmic tail without a signaling motif, shares the critical adaptor molecule, CARD9, that is critical during protection against cryptococcal infections and is necessary for anti-fungal immunity in humans." (PMID 28107361, 2017).
gastric cancer (5 papers, 2017 to 2024). A primary or metastatic malignant neoplasm involving the stomach. "Furthermore, results from Protein Atlas database validate immune molecules including CD86, CD209, C3AR1, CLEC4D, CLEC7A and CYSLTR2 are positive in gastric cancer cells." (PMID 29152078, 2017).
autoimmune disease (4 papers, 2011 to 2026). A disorder resulting from loss of function or tissue destruction of an organ or multiple organs, arising from humoral or cellular immune responses of the individual to their own tissue constituents. "Our results point to the contribution of the CLEC4D gene to the onset of AA in the Jordanian population and elucidate an additional emphasis on the genetic basis of the disease, the role of immune-related genes in its etiology, and the risk SNPs shared with other autoimmune diseases." (PMID 39459398, 2024).
ischemic stroke (4 papers, 2021 to 2025). A stroke disorder caused by obstruction of blood flow to the brain, due to thrombotic (local blood clot formation) or embolic (due to a blood clot or other material traveling from another site) event. "From a clinical translation perspective, CLEC4D and its associated signaling pathways represent promising therapeutic targets for ischemic stroke." (PMID 40313716, 2025). "C-type lectin domain family 4 member D (CLEC4D) and mast cell expressed membrane protein 1 (MCEMP1) are identified to be potential prognostic and diagnostic biomarkers for ischemic stroke." (PMID 34957234, 2021). "In summary, this study not only identifies the abnormal expression of key genes such as CLEC4D in ischemic stroke through large-scale data mining but also proposes a hypothesis that CLEC4D may regulate the balance between inflammation activation and UPRmt through multiple signaling pathways." (PMID 40313716, 2025). "Moreover, studies have shown that the relative mRNA expression of CLEC4D in peripheral blood of patients suffering ischemic stroke within 24 h after onset was dramatically increased, compared with the normal control group, which was consistent with our analysis results." (PMID 35075378, 2022).
lupus (4 papers, 2021 to 2024). "The expression of CLEC4D was associated with an up-regulated pathway of Neutrophil extracellular trap formation, PPAR signaling pathway, Staphylococcus aureus infection, Systemic lupus erythematosus, TNF signaling pathway, and Toll−like receptor signaling pathway." (PMID 36979470, 2023).
pulmonary tuberculosis (4 papers, 2015 to 2024). A bacterial infection that affects the lungs and is caused by Mycobacterium tuberculosis. "In humans, a polymorphism in the CLEC4D gene that results in reduced expression, is associated with increased susceptibility to pulmonary tuberculosis." (PMID 33424774, 2020). "Furthermore, a polymorphism of Clec4d in humans, which caused reduced surface expression of the receptor, is associated with increased susceptibility to pulmonary tuberculosis." (PMID 26558717, 2016). "Importantly, this increased Clec4d expression during infection is reflective of the transcriptional upregulation of this receptor that we had observed in patients suffering from pulmonary tuberculosis." (PMID 26558717, 2016).
hepatocellular carcinoma (3 papers, 2022 to 2025). A malignant tumor that arises from hepatocytes. "The mRNA expression level of CLEC4D was reported to be significantly lower in hepatocellular carcinoma." (PMID 36552262, 2022). "For example, in hepatocellular carcinoma (HCC), increased expression of CLEC4D has been observed and correlated with poor prognosis and tumor invasiveness." (PMID 37745724, 2023).
arrhythmogenic right ventricular cardiomyopathy (2 papers, 2023). "The expression of CLEC4D was associated with a down-regulated pathway of alanine, aspartate, and glutamate metabolism, Arrhythmogenic right ventricular cardiomyopathy, Basal cell carcinoma, DNA replication, and so on." (PMID 36979470, 2023).
depression (2 papers, 2022 to 2025). "Additionally, air pollution can activate inflammatory response pathways (e.g., IL1RN, galectin-3, CLEC4D, CASP8), disrupting neurotransmitter balance and exacerbating neuronal inflammation, thereby increasing the incidence of depression." (PMID 40611827, 2025).
Stroke (2 papers, 2022 to 2025). Sudden impairment of blood flow to a part of the brain due to occlusion or rupture of an artery to the brain. "The upregulation of CLEC4D may be closely associated with neutrophil recruitment, activation, and the exacerbation of inflammatory responses, highlighting its potential role as a key regulator of post-stroke inflammation." (PMID 40313716, 2025). "In dataset GSE16561, with the threshold of p < 0.05, CLEC4D, GPR97, MCEMP1, and TSPAN14 were significantly upregulated in the stroke group (The platform GPL6883 did not explore FPR2's expression)." (PMID 35075378, 2022).
vasculitis (2 papers, 2018 to 2020). "Inflammatory molecules of haptoglobin (HP), C-Type Lectin Domain Family 4 Member D (CLEC4D), and G-protein coupled receptor 84 (GPR84) are glycoproteins involved in cardiovascular disease and vasculitis." (PMID 33344384, 2020).
anaphylaxis (1 paper, 2023). An acute hypersensitivity reaction that occurs from exposure to an allergen. "Hub genes identified here (IL1R2, FOS, MMP9, DUSP1, and CLEC4D) represent a whole blood gene signature of anaphylaxis with STEMI predisposition and provide candidate diagnostic and therapeutic targets for follow-up studies." (PMID 37469874, 2023). "Taken together, these results suggested that two hub genes, DUSP1 and CLEC4D, held a promise for the diagnosis of anaphylaxis complicated STEMI as blood diagnostic biomarkers." (PMID 37469874, 2023). "IL1R2, FOS, MMP9, DUSP1, and CLEC4D were screened and identified as hub genes shared by anaphylaxis and STEMI." (PMID 37469874, 2023). "Taking the intersection of six algorithms (DMNC, Stress, MCC, Degree, Closeness, Radiality) in cytoHubba, we found 6 hub genes shared by anaphylaxis and STEMI: IL1R2, S100A12, FOS, MMP9, DUSP1, and CLEC4D." (PMID 37469874, 2023).
Aortic dissection (1 paper, 2022). Aortic dissection refers to a tear in the intimal layer of the aorta causing a separation between the intima and the medial layers of the aorta. "AGFG1, MCEMP1, IRAK3, KCNE1, and CLEC4D in module M37 were highly connected and strongly linked with AD, suggesting that these genes may help understand the pathogenesis of aortic dissection." (PMID 35178459, 2022).
cardioembolic stroke (1 paper, 2022). "Additionally, our study indicated that CLEC4D was positively correlated with neutrophils and T cells CD4 memory activated, while negatively associated with T cells CD8, which implied that CLEC4D might act through an inflammatory mechanism dependent upon immune effectors in cardioembolic stroke." (PMID 35075378, 2022).
chronic myelogenous leukemia (1 paper, 2025). "GSEA showed that CLEC4D was enriched in 37 functional pathways, with the top three being chronic myeloid leukemia, ubiquitin-mediated proteolysis, and protein export signaling pathway." (PMID 40313716, 2025). "Our GSEA further revealed that CLEC4D is significantly enriched in pathways such as chronic myelogenous leukemia (CML), involving critical signaling pathways like JAK-STAT, MAPK, and PI3K-AKT." (PMID 40313716, 2025).
ischemia (1 paper, 2025). A hypoperfusion of the BLOOD through an organ or tissue caused by a PATHOLOGIC CONSTRICTION or obstruction of its BLOOD VESSELS, or an absence of BLOOD CIRCULATION. "Furthermore, monitoring the dynamic changes of CLEC4D and its downstream signaling pathways at different time points post-ischemia will help clarify its spatiotemporal-specific functions in acute inflammatory responses and repair processes." (PMID 40313716, 2025).
lung carcinoma (1 paper, 2023). "We found Retinoic acid receptor responder protein 1, C-type lectin domain family 4 member D was significantly positively associated with lung cancer." (PMID 37745724, 2023). "HannumAge acceleration may increase the risk of lung cancer, some of which may be mediated by CLEC4D and RARR-1, suggestion that CLEC4D and RARR-1 may serve as potential drug targets for the treatment of lung cancer." (PMID 37745724, 2023). "In study, the results of mediator MR imaging showed that Epigenic Clockscould increase the concentration of proteins such as C-type lectin domain family 4 member D (CLEC4D), Retinoic acid receptor responder protein 1, leading to lung cancer." (PMID 37745724, 2023).
osteosarcoma (1 paper, 2022). A usually aggressive malignant bone-forming mesenchymal neoplasm, predominantly affecting adolescents and young adults. "Interestingly, B cells in TNF‐Tg SBM also show increased levels of C‐type lectin domain family gene CLEC4D and CLEC4E, suggesting that the CLEC11A+ B cells in osteosarcoma may have similar biological functions as the TNF‐Tg SBM‐derived B cells." (PMID 36305631, 2022).
pancreatic ductal adenocarcinoma (1 paper, 2022). An infiltrating adenocarcinoma that arises from the epithelial cells of the pancreas. "CLEC4D (Dectin-2 cluster′′ of C-type lectin receptor) is expressed exclusively by macrophages and is involved in the occurrence of pancreatic ductal adenocarcinoma." (PMID 35178459, 2022).